MRPL28 (mitochondrial ribosomal protein L28)
Synonyms: MAAT1; p15; bL28m
Tractability: Small molecule: a structure with a bound ligand is known. PROTAC: ubiquitination databases record sites on it; its protein half-life has been measured.
Gene: Protein-coding gene on chromosome 16 (365,916 to 371,289, reverse strand). Ensembl gene ENSG00000086504.
Subcellular location: Mitochondrion
Subcellular location (Human Protein Atlas): Mitochondria
Pathways (Reactome):
Metabolism of proteins: Mitochondrial ribosome-associated quality control; Mitochondrial translation elongation; Mitochondrial translation initiation; Mitochondrial translation termination
Gene Ontology:
Molecular function: protein binding; RNA binding; structural constituent of ribosome
Biological process: mitochondrial translation; translation
Cellular component: mitochondrial large ribosomal subunit; mitochondrial ribosome; mitochondrion; mitochondrial inner membrane
Genetic constraint (gnomAD): Loss-of-function variants: 31 observed, 31.13 expected, observed/expected ratio (o/e) 1, 90% interval 0.75 to 1.34. The synonymous counts are far from expectation, so gnomAD's model fits this gene poorly and the ratio says little. Missense variants: 432 observed, 331.67 expected, observed/expected ratio (o/e) 1.3, 90% interval 1.2 to 1.41. Synonymous variants: 227 observed, 140.62 expected, observed/expected ratio (o/e) 1.61, 90% interval 1.45 to 1.8.
Homologues: Orthologues: chimpanzee MRPL28 (99% identical), macaque MRPL28 (96% identical), guinea pig MRPL28 (88% identical), mouse Mrpl28 (84% identical), rat Mrpl28 (78% identical), pig MRPL28 (77% identical), dog MRPL28 (70% identical), tropical clawed frog mrpl28 (68% identical), zebrafish mrpl28 (66% identical), Caenorhabditis elegans mrpl-28 (40% identical), Drosophila melanogaster mRpL28 (35% identical).
Diseases named in the same sentence as MRPL28 in open-access papers:
MRPL28 is named in the same sentence as 11 diseases in open-access papers, as found by Europe PMC text mining. Sharing a sentence is not in itself a finding about the gene and the disease. The quoted sentences say what the papers report.
pancreatic tumor (3 papers, 2009 to 2021). "MRPL28 encodes mitochondrial ribosomal protein, and its low expression can reduce the mitochondrial activity of pancreatic tumor cells and increase glycolysis." (PMID 34630514, 2021). "We carried out a screen for loss of genetic elements in pancreatic tumor cells that accelerated their growth as tumors, and identified mitochondrial ribosomal protein L28 (MRPL28)." (PMID 19753307, 2009).
autoimmune disease (1 paper, 2012). A disorder resulting from loss of function or tissue destruction of an organ or multiple organs, arising from humoral or cellular immune responses of the individual to their own tissue constituents. "It is therefore difficult to speculate as to how reduced MRPL28 methylation might increase JIA risk, although mitochondrial dysfunction has been associated with autoimmune disease." (PMID 23148518, 2012).
breast carcinoma (1 paper, 2024). "According to these network analyses, it is suggested that MRPS30 may play a role in the apoptosis process and breast cancer development through interaction with DAP3, MLPL37, and MRPL28." (PMID 38886335, 2024).
gastric cancer (1 paper, 2022). A primary or metastatic malignant neoplasm involving the stomach. "For example, as a mitochondrial protein, MRPL28 can be used as a target for developing new drugs for gastric cancer." (PMID 35268153, 2022).
lung adenocarcinoma (1 paper, 2021). A carcinoma that arises from the lung and is characterized by the presence of malignant glandular epithelial cells. "Upregulation of MRPL22 (HR = 1.5, p = 0.0048), MRPL28 (HR = 1.5, p = 0.0098), MRPL21 (HR = 1.7, p = 0.001), MRPL12 (HR = 1.7, p = 0.00059), MRPS12 (HR = 1.6, p = 0.002), and MRPL17 (HR = 1.5, p = 0.0051) were correlated with poor overall survival in lung adenocarcinoma." (PMID 34925439, 2021). "The Cytoscape with cytoHubba tool kits, GEPIA, and c-BioPortal analysis suggested that upregulated hub genes of MRPL22, MRPL28, MRPL21, MRPL12, MRPS12, and MRPL17 are correlated with poor overall survival and may play a key role by cooperating with ALDOA in lung adenocarcinoma." (PMID 34925439, 2021).
tumor (4 papers, 2009 to 2024). "Other MRPs such as MrpL11, MrpL12 and MrpL28 have been reported to be differentially expressed in tumour cells or tissue." (PMID 28056857, 2017). "Knockdown of MRPL28 in either of these cell lines resulted in approximately a 2–3 fold increase in tumor growth." (PMID 19753307, 2009). "We found that the MRPL28 knockdown tumors had a significant reduction in the overall hypoxic fraction within the tumor when compared to sizxe matched controls." (PMID 19753307, 2009). "Existing studies have suggested that MRPL37 and MRPL28 may be involved in cell transformation, proliferation, and apoptosis of tumor cells." (PMID 38886335, 2024). "We also found that expression of a truncated MRPL28 could increase tumor growth as well." (PMID 19753307, 2009).
cancer (2 papers, 2017 to 2022). A tumor composed of atypical neoplastic, often pleomorphic cells that invade other tissues. "Knock-down of MRPL28 in pancreatic tumour cells resulted in decreased mitochondrial activity, increased glycolysis, and accelerated growth in vivo, a phenomenon commonly observed in cancer cells (the Warburg effect)." (PMID 28056857, 2017).
MRPL28 also shares sentences with these, for which no sentence is quoted: asthma (2 papers); Anxiety (1); Obesity (1); pancreatic cancer (1).